CDO1 (cysteine dioxygenase type 1)
Diseases named in the same sentence as CDO1 in open-access papers (continued):
Sharing a sentence is not in itself a finding about the gene and the disease.
tumor (continued). "To further validate CDO1's tumour suppressive function, we employed CDO1 overexpression strategy in MDA‐MB‐231 and MCF‐7 cells, which demonstrated that CDO1 overexpression significantly inhibited cell proliferative, cell migrative and invasive capacities in vitro compared to the controls." (PMID 37740473, 2023). "CDO1 is a tumor suppressor in human cancers and can promote apoptosis." (PMID 36733341, 2023). "Additionally, tumor masses derived from CDO1-expressing MKN45 or NCI-N87 cells were much smaller than those from the control cells, and the weights of the collected xenograft tumors were also dramatically decreased as the result of CDO1 restoration." (PMID 36526626, 2022). "Also, the higher the hypermethylation frequency of CDO1, the lower the degree of tumor differentiation." (PMID 34246261, 2021). "CDO1 as a tumor suppressor gene always undergoes methylation changes early in tumor development." (PMID 32317090, 2020). "In the present study, the gene panel CDO1, SOX17, and HOXA7 showed the best diagnostic accuracy in the subgroup with tumor size 2.1-3 cm and decreased in subgroups with smaller tumor size, especially when the tumor size was less than 1 cm." (PMID 32138766, 2020). "Moreover, it has been reported that CDO1 is involved in tumor cell growth, cell migration, invasion, and the ability of colony formation." (PMID 30677088, 2019). "Further work is needed to determine whether Cdo1 impairs tumorigenesis in this model, and to evaluate the consequences of strategies to induce CDO1 expression on tumor growth and metabolism in vivo." (PMID 31107239, 2019). "Although CDO1 methylation abnormalities involved in carcinogenesis have been reported, the CDO1 oncogenic relevance during tumor progression remains unclear." (PMID 29746493, 2018). "CDO1 plays a role as a tumor suppressor gene and as a methylation-specific gene in human cancer." (PMID 29746493, 2018). "We recently confirmed the CDO1 gene as being specifically methylated in various human cancers following our development of an original algorithm designated as a pharmacological unmasking microarray (PUM), which suggested that CDO1 plays a tumor suppressive role in human carcinogenesis." (PMID 29161283, 2017). "Interestingly, two recent reports identified methylation and silencing of CDO1 as a common event in tumorigenesis, suggesting its role as a tumor suppressor gene." (PMID 24351290, 2014). "In addition, CDO1 displayed tumor suppressive activities in an in vitro cell culture and an in vivo mouse model." (PMID 23028699, 2012). "Moreover, forced expression of full-length CDO1 in human cancer cells markedly decreased the tumor cell growth in an in vitro cell culture and/or an in vivo mouse model, whereas knockdown of CDO1 increased cell growth in culture." (PMID 23028699, 2012). "In addition, a statistically significant difference in the frequency of CDO1 promoter methylation was observed between primary normal and tumor tissues derived from breast, esophagus, lung, bladder and stomach." (PMID 23028699, 2012). "Functional studies revealed that CDO1 harbors tumor suppressive activity." (PMID 23028699, 2012). "CDO1 DNA methylation was a significant marker in the pairwise multivariate analysis including age at surgery, pathological T stage, progesterone receptor status, tumor grade or endocrine therapy." (PMID 20515469, 2010). "However, regarding the mild tumor-suppressing effect of Cdo1, it could be possible that this epigenetic methylation is generated after carcinogenesis because cancer induced by Cdo1 silencing has not been found." (PMID 38672271, 2024). "Therefore, restoring CDO1 function or increasing the expression of CDO1 protein in tumors may render tumor cells more vulnerable to ferroptosis, resulting in decreased tumor viability and growth." (PMID 35280684, 2022).
tumor (continued). "Importantly, Keap1R554Q/R554Q tumors strongly expressed Cdo1, demonstrating that Nrf2 activation promotes Cdo1 accumulation under physiological conditions in vivo, and suggesting that Cdo1 may impede tumor progression." (PMID 31107239, 2019). "These functional data suggested that CDO1 hypermethylation may play a causative role in tumor progression of primary GBC, rather than in the results of progression." (PMID 29161283, 2017). "Moreover, Cdo1 has been reported as a tumor suppressor gene which is suppressed by DNA methylation." (PMID 24553827, 2014). "Hence, CDO1 is believed to be a critical tumor suppressor gene, and could be a marker of the chemo-resistance of cancer cells." (PMID 25469504, 2014). "Based on our previous data analysis and experimental validation, we have confirmed the anti-tumor function of DNMT3L and CDO1, and have demonstrated that DNMT3L can regulate both the DNA methylation and expression of CDO1." (PMID 38308276, 2024). "Collectively, these analytical findings further support the regulatory role of CDO1 in the cell cycle of HCC and suggest its potential significance in tumor metabolism." (PMID 38308276, 2024). "Silencing or inactivating CDO1 helps to restore cellular GSH contents to avoid ROS and lipid peroxidation, which increases the resistance to ferroptosis, and promotes tumor proliferation 54-56." (PMID 35280684, 2022). "Respectively, the expression of CDO1, CELF2, ITPRIPL1, KCNH8, RIC3, USP44 and ZSCAN23 was significantly lower in tumor tissues, whereas the expression of PTK6 and RAB25 was significantly higher in tumor tissues." (PMID 34056873, 2021). "Hypermethylation in tumor tissues beyond 60% was designated as highly relevant methylation gene (HRMG), and CDO1 gene is the most common HRMG among human cancers." (PMID 30934021, 2019). "Tumor location, pT, pN, pStage (Dukes classification), v, INF, and CDO1 TaqMeth V were significant prognostic factors for RFS." (PMID 29746493, 2018). "Next, to clarify the clinical significance of the methylation level of the CDO1 gene, Q-MSP assessment of the BC tumor tissues was also performed in 172 primary BC." (PMID 26785325, 2016). "To further study the tumor suppressor activity of CDO1 in CRC cell lines, we established clones stably expressing CDO1 and then selected clones with relatively high levels of CDO1 in HCT116 (pCDO1-#5 and pCDO1-Pool) and DLD-1 cells (pCDO1-#2)." (PMID 23028699, 2012). "Secondly, this study exclusively explored the potential mechanisms of CDO1 in HCC through data analysis, proposing that CDO1 may exert its role in HCC by regulating tumor metabolism." (PMID 38308276, 2024). "Further, we examined the promoter methylation levels of DELMRGs and found that several genes (such as OAS2, KALRN, SLC16A7, PER2) had significantly lower methylation levels in tumor samples, while several genes (SLC6A3, CDO1, and SERPINC1) were significantly higher methylated." (PMID 37795453, 2023). "Tumor growth requires NRF2 without CDO1 expression, so CDO1 hypermethylation with its gene silencing was recognized in MSI-H tumors." (PMID 34936649, 2021). "Furthermore, three-gene combinations detected even the smallest lung nodules, with the combination of CDO1, SOX17, and HOXA7 having the overall best performance, while the combination of CDO1, TAC1, and SOX17 was best in tumor sizes less than 1.0 cm." (PMID 32138766, 2020). "Using the best optimized cut-off value of TaqMeth V to discriminate tumor from non-cancerous tissues, CDO1 gene hypermethylation is found in 72~91% in various cancers." (PMID 30934021, 2019). "TaqMeth Vs were significantly higher in the tumor tissues than in the corresponding non-cancerous mucosa tissues for CDO1 (P < 0.0001), HOPX (P < 0.0001), and Reprimo (P = 0.0006), except for the E-cadherin (P = 0.08)." (PMID 31069006, 2019).
tumor (continued). "Although there was no statistical difference between CDO1 promoter methylation level to size of tumor (pT factor), lymph node metastasis (pN factor), UICC staging system, hormone receptor status, and Ki-67 status, but it tended toward with HER2 (p = 0.07)." (PMID 26785325, 2016). "For this purpose, we selected CpG sites within 200 bp from transcription start sites (TSS200) for two tumor-suppressor genes (cg22879515 (MIR34B), and cg23180938 (CDO1)), and assessed distributions of their β values obtained in the initial genome-wide methylation analysis." (PMID 24312652, 2013). "CDO1 expression was also examined using Cancer Profiling Array II which includes normalized cDNA of tumor and the matched non-cancerous (normal) tissues for 19 different types of cancers." (PMID 23028699, 2012). "The fact that cells remained cancerous in the presence of these two opposing effects suggests that the enhancement of the tumor-suppressing effect of Cdo1 was not weaker than the promotion of cysteine uptake by Nrf2, and that cells were protected from ferroptosis." (PMID 38672271, 2024). "Interestingly, while the combination of CDO1, SOX17, and HOXA7 showed the overall best performance in our patient cohort, the combination of CDO1, TAC1, and SOX17 had the best performance in the subgroup with tumor size less than 1.0 cm." (PMID 32138766, 2020). "On the other hand, we have recently identified CDO1 as genes methylated specifically in human cancers after developing algorithm utilizing pharmacological unmasking microarray (PUM) as well as others, suggesting that CDO1 plays a tumor suppressive role in human carcinogenesis." (PMID 26785325, 2016). "Moreover, through the integration of big data analysis and experimental validation, we have clarified the anti-tumor activity of CDO1 in HCC, and the rescue experiments have shown that DNMT3L can effectively suppress tumor growth and metastasis by regulating CDO1." (PMID 38308276, 2024). "First, the degree of hypermethylation of the specific DNA promoter regions of the 4 methylation genes (CDO1, HOPX, Reprimo, and E-cadherin) was assessed in tumor tissues and the corresponding non-cancerous mucosa tissues in 58 RGC patients." (PMID 31069006, 2019). "The top differentially expressed transcripts between tumor and non-tumor were TPX2, DCBLD2 and ANLN which were significantly increased in tumors (T∶N ratio>2.0, P<0.01), and CDO1, DPEP1, C7, ALDH1A1 and NR3C2 which were significantly decreased in tumors (T∶N ratio<0.2, P<0.01)." (PMID 22363658, 2012).
cancer (49 papers, 2012 to 2026). A tumor composed of atypical neoplastic, often pleomorphic cells that invade other tissues. "Given the potential of serum methylation biomarkers as non‐invasive tools for cancer screening and prognosis prediction, we evaluated the early diagnostic value of serum CDO1 for BC." (PMID 37740473, 2023). "In this study, we showed cancer-specific methylation of CDO1 in SBC, its association with clinical malignancy, and its potential to function as a recurrence prediction marker." (PMID 30677088, 2019). "Aberrant promoter DNA methylation of the cysteine dioxygenase 1 (CDO1) gene is found in various human cancers and is associated with clinical outcome." (PMID 29161283, 2017). "Promoter NA methylation of CDO1 was demonstrated for the first time to be a cancer-associated methylation in primary GBC, and it has the potential to be a prognostic biomarker of GBC for high-risk patients with stage II GBC." (PMID 29161283, 2017). "We also examined methylation status of the CDO1 promoter in each cell line by bisulfite-sequencing, and found that cancer cell lines with CDO1 loss harbored a dense methylation in the CDO1 promoter (indicated as M)." (PMID 23028699, 2012). "Detection and quantification of CDO1 methylation deserves further attention as a diagnostic biomarker of major human cancers due to its high frequency in primary tumors and near absence in normal tissues." (PMID 23028699, 2012). "Moreover, Cdo1 mutation can be seen in every cancer type, but only in a low percentage, with the highest percentage in lung cancer being still less than 10%." (PMID 38672271, 2024). "Moreover, and importantly, a decrease in the active Cdo1 enzyme by mutation or downregulation can be seen in various types of cancers." (PMID 38672271, 2024). "The deficiency in CDO1 expression in multiple cancer types implicates its anti-cancer functions." (PMID 36526626, 2022). "In cancer, CDO1 is usually silenced by promoter methylation and this is associated with poor prognosis, implying that the shutting down of CDO1 expression favours cancer progression." (PMID 33223534, 2021). "The protein encoded by CDO1 affects mitochondrial function by converting cystine to cysteine sulfamic acid and inhibits the production of glutathione to promote apoptosis, and it has been used as a diagnostic marker in a variety of cancers." (PMID 33391342, 2020). "The deficiency of the cysteine dioxygenase 1 (CDO1) expression has been reported in lung, endometrial, breast, prostate, clear-cell renal cell, and gastrointestinal cancers to date, and this aberration correlates with poor survival outcomes in patients with the examined cancer types." (PMID 36526626, 2022). "Many cancers exhibit altered function of Cdo1, underscoring its crucial role in cancer cell survival." (PMID 38672271, 2024). "Owing to its frequent occurrence in cancers, Cdo1 methylation has become a biomarker for various types of cancers, and blood testing for the methylated Cdo1 promoter offers useful information in detecting cancer in patients." (PMID 38672271, 2024). "Based on the current literature, combined anticancer therapy ensuring high Cdo1 activity should be a powerful approach to ensure and enhance the effect of anti-cancer drugs and to impede the development of drug resistance in cancer cells." (PMID 38672271, 2024). "Currently, a large number of studies have confirmed that increasing the expression level of Cdo1 is able to inhibit cancer development by promoting cancer cell death, particularly by ferroptosis." (PMID 38672271, 2024). "To further investigate the potential anti-cancer effect of CDO1, we conducted in vivo functional experiments." (PMID 38308276, 2024). "In this review, we elaborate on how studying the anticancer role of Cdo1 in apoptosis and ferroptosis will open new avenues to treat cancer." (PMID 38672271, 2024).
cancer (continued). "Induced cell death as an important direction in cancer chemotherapy, where Cdo1 has been shown to increase the vulnerability of cells." (PMID 38672271, 2024). "Epigenetic silencing is cancer-specific, and the most obvious form is methylation of the Cdo1 promoter; generally, methylation of a gene’s promoter inhibits its transcription." (PMID 38672271, 2024). "As CDO is a methylation-specific gene in human cancers, CDO1 methylation has been reported in many cancers recently." (PMID 36733341, 2023). "Of all these, CDO1, a cancer-specific methylated gene, has been shown to play a cancer suppressor role in various cancers." (PMID 36911020, 2023). "Based on TCGA data, we compared CDO1 expression levels between 24 types of human cancer tissues and normal samples." (PMID 37740473, 2023). "Our results uncover the molecular underpinnings of CDO1 in the suppression of cancer cell proliferation." (PMID 36526626, 2022). "CDO1 is a putative tumor suppressor gene in human cancers, and its abnormal DNA methylation level has been studied in a variety of tumors." (PMID 34246261, 2021). "Ten hypomethylation samples (TaqMeth V = 0.1±0.2; all samples were non-cancerous mucosa) and 10 hypermethylation samples (TaqMethV = 156.3±4.9; all samples were cancer tissues) were used for CDO1 immunostaining." (PMID 30677088, 2019). "Anyway, CDO1 gene has an outstanding feature with regard to cancer-specific methylation in human cancer." (PMID 30934021, 2019). "CDO1 is a tumor suppressor gene, and methylation of its promoter region has been found in numerous cancers." (PMID 31779688, 2019). "CDO1 was identified as a methylation-specific gene in human cancer by a methylation gene identification method that used a pharmacological unmasking microarray method." (PMID 30677088, 2019). "The results of this study newly showed that cancer-specific CDO1 methylation abnormality is found even in SBC." (PMID 30677088, 2019). "A growing body of evidence indicated that CDO1 promoter methylation was correlated with many cancers." (PMID 31956659, 2019). "The CDO1 gene shows extremely cancer-specific hypermethylation, and it can be a prognostic marker in SBC." (PMID 30677088, 2019). "Thus, it was speculated that CDO1 expression was maintained by the transcriptional activity of the remaining unmethylated allele, even though the other allele was undergoing dense methylation in the cancer tissue." (PMID 30677088, 2019). "CDO1 is a methylation-specific gene in human cancer that was identified by a pharmacological unmasking microarray." (PMID 29746493, 2018). "Because CDO1 expression is inhibited by methylation in cancer cells, the production of glutathione is increased and resistance to reactive oxygen species is enhanced." (PMID 29746493, 2018). "Cysteine metabolism modified by aberrant expression of CDO1 gene is thus considered to play an important role in cancer cell stemness in TNBC." (PMID 26785325, 2016). "Using pharmacological unmasking microarray, we identified promoter DNA methylation of cysteine dioxygenase 1 (CDO1) gene in human cancer." (PMID 26785325, 2016). "Although CDO1 is clearly hypermethylated in cancer cell lines, the degree of CDO1 promoter hypermethylation of cloned CDO1 promoter sequences has not been determined." (PMID 25469504, 2014). "Based on these results, analysis of methylated DNA is a very promising candidate tool for blood diagnosis of cancer, and plasma CDO1 methylation that was the focus of this study considered as one such candidate DNA." (PMID 25469504, 2014). "Because such cancer-prone methylation is rare, analysis of CDO1 methylation has great clinical potential for detection of minimal residual disease in human body fluids such as blood." (PMID 25469504, 2014). "To investigate protein expression of CDO1, we performed immunohistochemical (IHC) staining using both colon and esophagus tissue arrays with normal and cancer tissues." (PMID 23028699, 2012).